VOPP1 (VOPP1 WW domain binding protein)
Description:
Increases the transcriptional activity of NFKB1 by facilitating its nuclear translocation, DNA-binding and associated apoptotic response, when overexpressed. May sequester WWOX in lysosomal vesicles and thereby regulate WWOX role as tumor suppressor.
Synonyms: ECop; GASP; FLJ20532; DKFZp564K0822; WBP1L2
Tractability: Antibody: UniProt predicts a signal peptide or a membrane-spanning region.
Gene: Protein-coding gene on chromosome 7 (55,436,056 to 55,572,988, reverse strand). Ensembl gene ENSG00000154978.
Subcellular location: Cytoplasmic vesicle membrane; Late endosome membrane; Lysosome membrane
Gene Ontology:
Molecular function: enzyme binding; protein binding; protein sequestering activity
Cellular component: cytoplasmic vesicle membrane; endosome; late endosome; late endosome membrane; lysosomal membrane; lysosome; organelle membrane
Genetic constraint (gnomAD): Loss-of-function variants: 8 observed, 14.28 expected, observed/expected ratio (o/e) 0.56, 90% interval 0.33 to 1.01. The upper end of that interval is the gene's LOEUF score, 1.01, which puts it in group 4 of 6, group 1 being the genes least tolerant of losing a copy. Missense variants: 143 observed, 159.87 expected, observed/expected ratio (o/e) 0.89, 90% interval 0.78 to 1.03. Synonymous variants: 63 observed, 59.68 expected, observed/expected ratio (o/e) 1.06, 90% interval 0.86 to 1.3.
Homologues: Orthologues: chimpanzee VOPP1 (100% identical), macaque VOPP1 (99% identical), dog VOPP1 (91% identical), mouse Vopp1 (90% identical), pig VOPP1 (90% identical), rat Vopp1 (90% identical), guinea pig VOPP1 (88% identical), tropical clawed frog vopp1 (73% identical), zebrafish vopp1b (55% identical), zebrafish vopp1a (38% identical).
Diseases named in the same sentence as VOPP1 in open-access papers:
VOPP1 is named in the same sentence as 27 diseases in open-access papers, as found by Europe PMC text mining. Sharing a sentence is not in itself a finding about the gene and the disease. The quoted sentences say what the papers report.
glioblastoma (6 papers, 2011 to 2023). The most malignant astrocytic tumor (WHO grade IV). "VOPP1, also known as glioblastoma-amplified secreted protein and EGFR-coamplified and overexpressed protein (ECOP), is upregulated in multiple human tumors, such as gastric cancer and squamous cell carcinoma." (PMID 34708039, 2021). "Overexpression of VOPP1 has been reported in several cancers such as a glioblastoma and head and neck, lung, gastric, and pancreatic carcinomas, which are malignancies commonly affected by WWOX loss of expression." (PMID 30285739, 2018). "VOPP1 overexpression has been observed in multiple malignancies such as glioblastoma and gastric, head and neck, lung, and breast cancers." (PMID 30285739, 2018). "Moreover, Prosurvival Protein 1 (VOPP1) shows increased expression in various cancer types, such as squamous cell carcinoma, colorectal cancer, glioblastoma and gastric cancer." (PMID 37925175, 2023). "VSTM2A, LANCL2, SEC61G and VOPP1 were also amplified and are reported in the literature as fusion genes with EGFR in some glioblastoma patients." (PMID 29844869, 2018).
colorectal cancer (3 papers, 2023 to 2025). A primary or metastatic malignant neoplasm that affects the colon or rectum. "Inhibition of HOTAIR reduced 5-FU resistance in colorectal cancer (CRC) via miR-218/VOPP1 axis." (PMID 40949794, 2025). "For example, lncRNA HOTAIR contributes to colorectal cancer and 5-FU resistance through the recruitment of EZH2 and subsequent silencing of miR-218, upregulation of VOPP1 expression and subsequent activation of the NF-κB/TS pathway." (PMID 37680988, 2023).
breast carcinoma (2 papers, 2016 to 2018). "We found that WWOX specifically co-precipitated with VOPP1 indicating that endogenous WWOX and VOPP1 were physically associated in breast cancer cells." (PMID 30285739, 2018). "All these observations support strongly that overexpression of VOPP1 induces breast cancer by impairing the tumor suppressive activity of WWOX." (PMID 30285739, 2018). "To confirm these findings, we interrogated the Oncomine database for VOPP1 expression in several additional breast cancer datasets and obtained similar results." (PMID 30285739, 2018). "To evaluate the prognostic value of the VOPP1 expression on breast cancer patients’ survival, we performed a univariate analysis." (PMID 30285739, 2018). "In breast cancer cells, VOPP1 sequestrates WWOX in lysosomes, impairs its ability to associate with p73α, and inhibits WWOX-dependent apoptosis." (PMID 30285739, 2018). "To examine the existence of endogenous VOPP1-WWOX complexes in breast cancer cells, we first evaluated the expression of VOPP1 transcripts and proteins in a series of ten human breast cancer cell lines." (PMID 30285739, 2018). "In this study, we defined VOPP1 as a new molecular partner and an inhibitor of the apoptotic function of WWOX in breast cancer cells." (PMID 30285739, 2018). "Since VOPP1 and WWOX have concomitant patterns of expression, we evaluated the presence of significant interaction between VOPP1 and WWOX expression on breast cancer metastasis-free survival rates." (PMID 30285739, 2018). "In light of the VOPP1 gene location within the 7p11.2 chromosomal region, which contains EGFR, and frequent amplification in several malignancies, including basal-like breast cancers, we investigated whether altered VOPP1 expression was due to gene amplification." (PMID 30285739, 2018). "Therefore, gene amplification was not the main mechanism leading to VOPP1 overexpression in breast cancers." (PMID 30285739, 2018).
cervical cancer (2 papers, 2021 to 2025). A primary or metastatic malignant neoplasm involving the cervix. "LINC01410 has been reported to be abnormally expressed in cervical cancer and promotes the growth and invasion of cancer cells by regulating the miR-2467/VOPP1 axis." (PMID 35087800, 2021). "In cervical cancer, LINC01410 can sponge miR-2467-3p and miR-532-5p, upregulating VOPP1 and promoting the accumulation of lipid droplets, which in turn enhances the proliferation, invasion, and migration of cervical cancer cells." (PMID 41472748, 2025).
Sepsis (2 papers, 2021 to 2022). Sepsis is defined as life-threatening organ dysfunction caused by a dysregulated host response to infection. "Inhibition of VOPP1 expression in PBMCs alleviated the inflammatory response in advanced sepsis patients." (PMID 34708039, 2021). "One of the many mechanisms involved in the pathogenesis of sepsis is miR-218, which may be involved in reducing the inflammatory response by decreasing the expression of VOPP1 via the JAK /STAT axis." (PMID 36012630, 2022).
Arthritis (1 paper, 2021). Inflammation of a joint. "Further study of VOPP1 in SCI pathological process may bring insights into refining therapeutic regimens, as well as other disease states that are associated with elevated VOPP1 activity, such as asthma, arthritis, chronic/acute inflammation, and diverse tumors." (PMID 34708039, 2021).
breast tumors (1 paper, 2018). "After adjusting for standard clinicopathological prognostic factors, VOPP1 expression remained an independent prognostic factor in luminal B breast tumors (p = 0.003)." (PMID 30285739, 2018). "Relative expression of VOPP1 was significantly increased in the primary breast tumors (p = 8.10−4, Mann-Whitney U test)." (PMID 30285739, 2018). "In line with studies on other tumor types, we found that 25% of breast tumors (112/448) showed VOPP1 overexpression (≥ 2.5-fold increase as compared to expression in normal breast tissue)." (PMID 30285739, 2018). "All subgroups of breast tumors showed an increased level of VOPP1 transcripts (p = 1.10−3, 1.10−3, 1.10−4, and 6.10−3, respectively)." (PMID 30285739, 2018). "VOPP1 is overexpressed in breast tumors, especially in tumors that retain WWOX." (PMID 30285739, 2018). "Moreover, we showed that VOPP1 was overexpressed in breast tumors; this overexpression was predominant in tumors that retained WWOX expression and was associated with reduced metastasis-free survival of patients with WWOX-positive tumors." (PMID 30285739, 2018). "Next, we examined VOPP1 protein expression in a series of 24 human breast tumors." (PMID 30285739, 2018). "In accordance with our qRT-PCR results, breast tumors showed increased expression of VOPP1 protein (p = 0.0002) and this higher expression was not linked to any specific breast tumor subtype." (PMID 30285739, 2018). "Consistent with this possibility, by studying our series of 448 breast tumors, we found that the alteration of WWOX function, considered either by underexpression of WWOX or by overexpression of VOPP1, affects 81.69% (364/448) of breast tumors." (PMID 30285739, 2018). "We next examined the concomitant expression of VOPP1 and WWOX in our series of breast tumors." (PMID 30285739, 2018).
ganglioglioma (1 paper, 2025). A well differentiated, slow growing neuroepithelial neoplasm composed of neoplastic, mature ganglion cells and neoplastic glial cells. "Here, we present a case of a VOPP1::EGFR fusion associated with downstream NFκB pathway activation as a novel molecular alteration in ganglioglioma." (PMID 40234994, 2025). "Here, we report for the first time a gene fusion between epidermal growth factor receptor (EGFR) and vesicular, overexpressed in cancer, prosurvival protein 1 (VOPP1) as a potential oncogenic driver in a glioneuronal tumor morphologically resembling ganglioglioma." (PMID 40234994, 2025). "Since there is no histological or molecular evidence supporting the diagnosis of other glioneural tumors (e.g., PLNTY, DNT, gangliocytoma), the tumor should be regarded as a glioneural tumor with histological features of ganglioglioma and VOPP1::EGFR fusion, not elsewhere classified (NEC)." (PMID 40234994, 2025).
gastric adenocarcinoma (1 paper, 2018). "VOPP1, also known as ECop (EGFR-coamplified and overexpressed protein), is overexpressed in esophageal squamous cell and gastric adenocarcinoma." (PMID 30214895, 2018).
glioma (1 paper, 2019). A benign or malignant brain and spinal cord tumor that arises from glial cells (astrocytes, oligodendrocytes, ependymal cells). "For example, VOPP1 and CDKN2A, which have been proved important in glioma, were linked by KCTD5 in GBM." (PMID 31719831, 2019).
invasive breast carcinoma (1 paper, 2020). A carcinoma that infiltrates the breast parenchyma. "The gene expressions of ACOT7, STAT1, TYMP, and VOPP1 were significantly increased in invasive breast carcinoma, while the gene expressions of ACTG2, CNN1, CDC14B, NFIB, RCN1, and TRIM2 were dramatically downregulated in BRCA." (PMID 31986487, 2020).
oral squamous cell carcinoma (1 paper, 2023). "The expression of AXL, SCG5, VOPP1, DCBLD2 and DRAM in oral squamous cell carcinoma were significantly higher in the TCGA database than in normal tissues." (PMID 37925175, 2023).
ovarian carcinoma (1 paper, 2025). A malignant neoplasm originating from the surface ovarian epithelium. "Therefore, WNT and Notch are pivotal regulators of EMT process in ovarian cancer and we hypothesized that VOPP1 can suppress the EMT process through regulation of WNT and Notch pathways." (PMID 40949794, 2025). "Considering the role of NF-κB, WNT, and NOTCH network in tumor microenvironment and the lack of reports on the role of VOPP1 in ovarian cancer, we investigated its role in regulation of EMT process and drug resistance via WNT and NOTCH pathways." (PMID 40949794, 2025).
ovarian tumor (1 paper, 2025). "VOPP1 reduced ovarian tumor cell migration and PTX resistance via regulation of NOTCH and WNT mediated EMT process." (PMID 40949794, 2025). "Regarding the key role of WNT and NOTCH pathways in EMT process and drug response of tumor cells, we assessed for a probable interaction between the VOPP1 and these signaling pathways in ovarian tumor cells." (PMID 40949794, 2025). "VOPP1 reduced PTX resistance in ovarian tumor cells by regulation of ABCC4." (PMID 40949794, 2025). "We also observed that VOPP1 up regulated APC while down regulated β-catenin in ovarian tumor cells." (PMID 40949794, 2025). "Thus, in this study we investigated the role of VOPP1 in ovarian tumor progression." (PMID 40949794, 2025). "This indicates that VOPP1 as a part of NF-κB pathway can modulate WNT pathway via the downregulation of β-catenin and TCF/LEF complex in ovarian tumor cells." (PMID 40949794, 2025). "Our study highlighted the pivotal role of VOPP1 as a negative regulator of WNT/β-catenin and NOTCH pathways in ovarian tumor cells." (PMID 40949794, 2025). "VOPP1 significantly reduced EMT and cell migration in ovarian tumor cells." (PMID 40949794, 2025).
tongue squamous cell carcinoma (1 paper, 2023). A squamous cell carcinoma that arises from the tongue. "Eight genes were shown to be related to the prognosis in patients with tongue squamous cell carcinoma (AXL, SCG5, VOPP1, DCBLD2, DRAM, DUSP1, AQP5, BLNK)." (PMID 37925175, 2023).
cancer (15 papers, 2011 to 2025). A tumor composed of atypical neoplastic, often pleomorphic cells that invade other tissues. "VOPP1 (also known as Vesicular, Overexpressed in cancer, Prosurvival Protein 1 or EGFR-Co-amplified and Overexpressed Protein) expression is shown first in relation to EGFR expression, then to PCNA expression." (PMID 31857847, 2019). "Our results suggest that VOPP1 promotes cancer by inhibiting WWOX-dependent apoptosis; however, we cannot exclude the possibility that VOPP1 acts on cancer by impairing other WWOX functions." (PMID 30285739, 2018). "In the frontal section, no gene was substantially down-regulated, but several were down-regulated by approximately a −2-fold, topped by VOPP1 (vesicular, overexpressed in cancer, pro-survival protein 1) with a fold change of −2.7." (PMID 29632138, 2018). "Predicted interacting proteins include DENN/MADD domain containing 5B (DENND5B) and vesicular, overexpressed in cancer, prosurvival protein 1 (VOPP1)." (PMID 27096627, 2016). "Interestingly, in different cellular models, VOPP1 depletion resulted in apoptosis, while ectopic expression conferred a pro-survival phenotype to cancer cells, which strongly suggested VOPP1 as an anti-apoptotic protein." (PMID 30285739, 2018). "Therefore, the altered expression of WWOX and aberrant localization should be more precisely scrutinized in these cancers; further studies on this pathway may provide a better assessment of the WWOX/VOPP1 axis in human cancers." (PMID 30285739, 2018). "VOPP1, also known as EGFR-coamplified and overexpressed protein, is a critical regulator of apoptosis and growth in cancer cells that primarily acts through the NF-κB pathway." (PMID 40949794, 2025). "The eight mRNAs selected for further analysis, AXL, SCG5, VOPP1, DCBLD2 and DRAM1 are cancer-promoting genes, DUSP1, AQP5 and BLNK are cancer suppressor genes." (PMID 37925175, 2023). "The results revealed five cancer-promoting genes (AXL, SCG5, VOPP1, DCBLD2, DRAM1), and three tumor suppressor genes (DUSP1, AQP5, BLNK)." (PMID 37925175, 2023). "Conversely, WWOX-mediated cell death in A549 cancer cells was overcome by ectopic expression of VOPP1 but not VOPP1Y165A indicating that VOPP1 overexpression inhibited WWOX-dependent apoptosis." (PMID 30285739, 2018). "Similar to the PTEN tumor suppressor, differences in the types of neoplasias observed in these animal models might be due to the regulation of WWOX by various molecular mechanisms, including VOPP1-mediated relocation, which generates dosage-dependent WWOX functions in human cancers." (PMID 30285739, 2018).
tumor (6 papers, 2010 to 2025). "VOPP1 has been associated with increased tumor cell survival in gastric cancer." (PMID 40949794, 2025). "Considering the importance of cross talks between different signaling pathways during tumor progression, we assessed the role of VOPP1 in OC progression through the modulation of WNT and NOTCH pathways." (PMID 40949794, 2025). "VOPP1 is an activator of NF-κB pathway during tumor progression." (PMID 40949794, 2025). "VOPP1 has a dual role as either an oncogene or tumor suppressor, depending on the cellular context." (PMID 40949794, 2025). "Therefore, VOPP1 can be considered as a potential target for overcoming drug resistance and inhibiting tumor metastasis in OC patients following further animal studies and clinical trials." (PMID 40949794, 2025). "VOPP1 also exerts its regulatory functions by modulating the lncRNA-miR-mRNA axes in tumor cells." (PMID 40949794, 2025). "VOPP1 facilitates the localization of WWOX protein within lysosomes, preventing its interaction with p73α, thereby suppressing apoptosis and promoting tumor progression." (PMID 40949794, 2025). "Two genes (LANCL2 and VOPP1) and SEPT14 were respectively amplified in 3 and 2 tumours." (PMID 21170331, 2010). "ND GBM pre-surgery saliva (NDT0) showed the exclusive characterization of peptide fragments of CDA, HOPX, FABP5, WIPF3, VOPP1, AHNAK, and DAZAP1 proteins, which, to the best of our knowledge, have not been previously identified in relation to GBM tumor." (PMID 41155285, 2025).
VOPP1 also shares sentences with these, for which no sentence is quoted: squamous cell carcinoma (4 papers); atherosclerosis (2); gastric cancer (2); Alzheimer disease (1); asthma (1); infection (1); pancreatic carcinomas (1); periodontitis (1); Sleep apnea (1); viral infection (1).